ICOSLG (inducible T cell costimulator ligand)
Diseases named in the same sentence as ICOSLG in open-access papers (continued):
Sharing a sentence is not in itself a finding about the gene and the disease.
leukemia (1 paper, 2026). A malignant (clonal) hematologic disorder, involving hematopoietic stem cells and characterized by the presence of primitive or atypical myeloid or lymphoid cells in the bone marrow and the blood. "Statistically significant differences between the leukemia and MRD-negative groups were achieved by JUP, NT5C3B, MYC, GATA3, PTK7, CNP, SNAI1, and ICOSLG." (PMID 41596324, 2026). "High expression of JUP, NT5C3B, MYC, GATA3, PTK7, CNP, and ICOSLG clearly differentiated the leukemia from the non-leukemia group." (PMID 41596324, 2026). "Importantly, JUP, NT5C3B, MYC, and GATA3, PTK7, CNP, and ICOSLG differentiated both non-pathological conditions (non-leukemia and MRD-negative) from leukemia samples." (PMID 41596324, 2026).
liver diseases (1 paper, 2022). "ICOSLG was significantly up-regulated at both mRNA and protein level in samples from patients with a variety of liver diseases of both metabolic and immune etiologies." (PMID 35618311, 2022).
ovarian clear cell cancer (1 paper, 2022). An invasive malignant neoplasm that arises from the ovary and is characterized by a predominance of clear and hobnail malignant epithelial cells. "ICOSLG predicted overall survival with ovarian clear cell cancer via the Kaplan–Meier curve in our study." (PMID 35159096, 2022).
pneumonia (1 paper, 2019). An acute, acute and chronic, or chronic inflammation focally or diffusely affecting the lung parenchyma, caused by an infection in one or both of the lungs (by bacteria, viruses, fungi, or mycoplasma.). "Moreover, the expression of eight DEPs (PECAM1, PGLYRP1, AHCY, BHMT, EML3, ICOSLG, IGHV3‐23 and RTN4RL2) in normal and pneumonia groups (two patients) was quite different from that in the KD group." (PMID 30761252, 2019). "Moreover, the expression of eight of these 30 DEPs (PECAM1, PGLYRP1, AHCY, BHMT, EML3, ICOSLG, IGHV3‐23 and RTN4RL2) clustered normal and pneumonia samples into one group and clustered KD samples into another group, which heightens the importance of these eight DEPs in KD." (PMID 30761252, 2019).
tumor (185 papers, 2003 to 2026). "One the other hand, ICOSLG has been established as an immune checkpoint molecule that is closely associated with immune activation and tumor progression." (PMID 37605192, 2023). "ICOSLG was expressed in the cell membrane and cytoplasm of tumor cells (TCs), cancer-associated fibroblasts (CAFs) and tumor infiltrating lymphocytes (TILs) in 105 patients with OSCC." (PMID 37842091, 2023). "This was also the case for ICOSLG, although less consistent, and with additional expression in tumor-associated oligodendrocytes." (PMID 34286278, 2021). "In addition, considering that tumor cells can be used as the main mechanism of immune resistance through the immune checkpoint pathway, we further studied the association between ICOSLG and immune checkpoint molecules." (PMID 37842091, 2023). "Furthermore, analysis of tumor-infiltrating myeloid cells showed that CD206+C1QC+ TAM express high levels of MHC I and costimulatory receptors such as CD86 and ICOSLG compared with tumor-associated cDC1." (PMID 35503656, 2022). "During tumor development, ICOSLG can both promote and suppress tumor progression, since it activates Tconv cells and, at the same time, induces Tregs through NF-κB signaling." (PMID 40895574, 2025). "As a co-stimulator of T cells, ICOSLG has also received much attention in the tumor microenvironment and its immune escape process." (PMID 37842091, 2023). "In summary, we determined that ICOSLG was associated with the survival of OSCC patients and had a significant tumor-promoting effect." (PMID 37842091, 2023). "A B-cell associated signature distinguished HPV(+) from HPV(−) tumors, and included the DEGs CD200, GGA2, ADAM28, STAG3, SPIB, VCAM1, BCL2 and ICOSLG; the immune signal relative to T-cells was qualitatively similar between TILs of both tumor cohorts." (PMID 27462861, 2016). "ICOSLG is an immune checkpoint expressed by antigen-presenting cells and other cell types, including mesenchymal stem cells, endothelial cells, fibroblasts, and tumor cells." (PMID 39596506, 2024). "In addition, ICOSLG was positively correlated with Foxp3+ cells and negatively correlated with CD4+ T cells, indicating that ICOSLG is closely related to the immunosuppressive process in the tumor microenvironment." (PMID 37842091, 2023). "Therefore, we conclude that ICOSLG is actually involved in the occurrence and development of tumors, and can regulate the behavior of tumor cells and affect the changes of tumor microenvironment." (PMID 37842091, 2023). "However, the specific mechanism and related molecular pathways of ICOSLG in OSCC for immune regulation in tumor microenvironment remain to be further studied." (PMID 37842091, 2023). "Interestingly, expression levels of MHC I (HLA-A) and costimulatory receptors such as CD86, ICOSLG, and CLEC4A were high in tumor-associated CD206+ Macro_C1QC even compared with tumor-associated cDC1_CLEC9A." (PMID 35503656, 2022). "Also, 22 variants in five genes [ICOSLG, NCOR1, KMT2C, HLA-A and AR] were found to be pathogenic/ likely pathogenic in other tumor types." (PMID 33075099, 2020). "Therefore, an autocrine stimulation of the tumor cells via ICOSLG could be a possible explanation, particularly since in the gene expression analysis ICOSLG was expressed in the tumor cells of all NLPHL and THRLBCL cases." (PMID 24244368, 2013). "The interaction between ICOSLG and its receptor, ICOS, promotes the development of T regulatory cells in healthy bone marrow as well as in different tumor microenvironments." (PMID 41596324, 2026). "This signature, comprising CCL19, ICOSLG, IL11, PTGES, TNFAIP3, and TRAF3IP3, has been demonstrated to predict survival outcomes across a range of cancers and to correlate with tumor progression at the level of multi‐omics." (PMID 40714831, 2025). "Our analysis also identified a subset of tumor-infiltrating pDCs in most of the MF samples that expressed TGFB1, ICOSLG, and LILRA4." (PMID 37669110, 2023).
tumor (continued). "In both tumor models, CD11b+F4/80hi TAM that coexpress high levels of CD206 also showed significantly high expression of costimulatory receptors CD86 and ICOSLG compared with the CD11b+F4/80dim TAM population." (PMID 35503656, 2022). "We also observed that S1P treatment in tumor cells inhibited the expression of TAP2, CD27, CD160, and ICOSLG genes, which are important for the immune cell activation needed for antitumor responses." (PMID 35289120, 2022). "These included genes consistent with pro-inflammatory immune responses (CD27, CD28, CD3e, CD8a, ICOS, ICOSLG, Pax5, TBX, GATA3, HLA-A, TNFSF14, GPR146), but also immune suppressive influences in the tumor immune microenvironment (CTLA-4, FoxP3, PD-1)." (PMID 36698398, 2022). "LAG3, TIM3, ICOSLG, VISTA, GITR and CD40 were all detected in a majority of the 20 tumor subcohort over an abundance range between 10- and 40-fold." (PMID 32555523, 2020). "To explore whether the immune cell subsets of tumor tissues with high expression of ICOSLGTCs in OSCC patients changed, we determined the ICOSLG, CD4, CD8, CD19, CD68 and Foxp3 level of tumor centers and infiltration fronts in serial sections." (PMID 37842091, 2023). "Strong correlations between expression of AP001056.1 and ICOSLG were seen in several types of cancer, whereas, the most significant impact on overall survival was seen in SCCHN, making it an interesting lncRNA for this tumor type." (PMID 30862109, 2019). "However, the expression of miR-326 has no substantial relevance to ICOSLG in primary tumor and lymph node metastatic tissues." (PMID 34131111, 2021). "We then compared plasma levels of IL-8 and ICOSLG from 8 patients with immune profiles in conditioned media and RNA sequencing from paired GBM cell lines to investigate whether there was a correlation between plasma protein levels and tumor cell expression and secretion." (PMID 34286278, 2021).
cancer (60 papers, 2013 to 2026). A tumor composed of atypical neoplastic, often pleomorphic cells that invade other tissues. "Our findings showed that MLKL was positively correlated with the expression of immune checkpoints such as PD1, PD-L1, PD-L2, and CTLA4 in most cancer types, except for ICOSLG, CD200, CEACAM1, HHLA2, and VTCN1 in BUC." (PMID 37000317, 2023). "We constructed HDAds encoding either inducible T cell costimulator ligand (ICOSL), OX40L, or 41BBL, for which agonistic antibodies have been tested in clinical trials, and confirmed cancer cell surface expression of these molecules after infection." (PMID 35681750, 2022). "Currently, several other B7 family ligands such as B7-H2 (a.k.a. inducible T cell costimulator ligand; ICOSL) and B7-H3 are being explored as novel immunotherapeutic targets in other cancer types." (PMID 33117354, 2020). "The prognostic effect of AP001056.1 and its correlation with ICOSLG mRNA levels in other TCGA cancer types was investigated using TANRIC." (PMID 30862109, 2019). "In addition, 21 of these genes were eGenes almost universally across cancer types including five putative long non-coding RNAs, genes known to play a role in the immune response (ICOSLG, ERAP2) and U2AF1, which is involved in spliceosome function." (PMID 35725412, 2022). "ETS2 was positively correlated with CD200, NRP1, ICOSLG, and TNFSF15 across several cancers." (PMID 36760475, 2023).
infection (27 papers, 2011 to 2025). The state of being infected such as from the introduction of a foreign agent such as serum, vaccine, antigenic substance or organism. "The T cell costimulators ICOSLG (inducible T cell costimulator ligand) and PD-L2 were downregulated during infection, as was butyrophilin subfamily 3 member A1 (BTN3A1), recently shown to present phosphoantigens to Vγ9Vδ2+ T cells." (PMID 24906157, 2014).
immune diseases (4 papers, 2017 to 2025). "Agents targeting ICOSLG, IL6R, and CD28 are broadly applied in managing immune system diseases." (PMID 40868097, 2025).
hematologic neoplasm (2 papers, 2019 to 2025). "In most hematological tumors, FOXP1 expression demonstrated a positive correlation with the expression levels of stimulatory immune genes such as ICOSLG, IL2RA, and HMGB1, and a negative correlation with the expression levels of inhibitory immune genes, such as SLAMF7." (PMID 40672953, 2025).
ICOSLG also shares sentences with these, for which no sentence is quoted: Autoimmunity (9 papers); rheumatoid arthritis (8); colon carcinoma (7); ovarian carcinoma (6); Arthritis (5); COVID-19 (5); uveitis (5); viral infections (5); acute myeloid leukemia (4); inflammation (4); invasive breast carcinoma (4); allergic asthma (3); Allergy (3); head and neck squamous cell carcinoma (3); immunodeficiencies (3); liver fibrosis (3); malaria (3); pancreatic cancer (3); parasite infection (3); schistosomiasis (3); B-cell lymphoma (2); bladder cancer (2); breast tumor (2); colorectal tumor (2); diabetes (2); endothelial dysfunction (2); fibrosis (2); follicular lymphoma (2); Granuloma (2); infectious disease (2).
A further 101 diseases each share a sentence with ICOSLG in 2 papers or fewer.